CD1C (CD1c molecule)
Diseases named in the same sentence as CD1C in open-access papers (continued):
Sharing a sentence is not in itself a finding about the gene and the disease.
acute myeloid leukaemia (2 papers, 2018 to 2025). "CD1c is expressed on several haematological malignancies, including B cell acute lymphoblastic leukaemia (B-ALL) and acute myeloid leukaemia (AML) in both adults and children." (PMID 40709176, 2025).
breast tumor (2 papers, 2020 to 2023). "We aligned CD1c+CD14+ cells infiltrating breast tumor-draining lymph node with blood DC3s compared to cDC2s and monocytes." (PMID 32610077, 2020). "CD1C is an important part of the TME and participates in immune activity regulation in breast tumors." (PMID 36755259, 2023).
chronic myelogenous leukemia (2 papers, 2018 to 2025). "As additional specificity controls, the C1R cell line (human B-cell lymphoblastoid line) was transduced with CD1c-β2m or CD1d-β2m and the K562 (chronic myelogenous leukemia) cell line was transduced with CD1c-β2m." (PMID 40777002, 2025).
Cirrhosis (2 papers, 2013 to 2023). A chronic disorder of the liver in which liver tissue becomes scarred and is partially replaced by regenerative nodules and fibrotic tissue resulting in loss of liver function. "We selected 8 patients with advanced cirrhosis for analyzing the genes of CD1c+ or CD14+ cells involved in the regulation and enzymatic pathways of the TCA cycle." (PMID 24322372, 2013).
coronary artery disease (2 papers, 2016 to 2024). "As expected, levels of several EV antigens (CD8, CD8, CD1c, CD25, CD62P, CD42a, CD86, CD44) increased in subjects displaying both OD and established cardiac disease (coronary artery disease, or chronic heart failure), as compared with those with only OD or cardiac disease." (PMID 39702460, 2024).
diffuse large B-cell lymphoma (2 papers, 2021 to 2023). "When we extended our analysis to evaluating CD1c expression in a broad range of tumor types using the Cancer Genome Atlas (TCGA), we also found significant overexpression in Diffuse Large B Cell Lymphoma (DLBCL) compared to normal tissue." (PMID 34381053, 2021).
dysplastic nevi (2 papers, 2017 to 2022). "Mean value of CD1c+ cells was significantly higher in dysplastic nevi in comparison with both melanoma in situ and invasive melanoma." (PMID 28331853, 2017). "In that location mean values of dendritic cell number in dysplastic nevi versus invasive melanomas were, respectively, 14.72 versus 16.82 for CD1a, 32.00 versus 35.20 for CD1c, 1.0 versus 0.82 for DC-LAMP+, and 3.22 versus 4.00 for DC-SIGN+." (PMID 28331853, 2017).
endometrial cancer (2 papers, 2023 to 2025). Primary or metastatic malignant neoplasm involving the endometrium (mucous membrane that lines the endometrial cavity). "We hypothesized that the broader array of antibodies used (anti-CD83, -DC-LAMP, -CD1a, -CD1c, -CD123, and -DC-SIGN) would clarify the correlation between DCs’ infiltrates and the clinicopathological features of endometrial cancers." (PMID 36768258, 2023).
endometriosis (2 papers, 2023 to 2025). The growth of functional endometrial tissue in anatomic sites outside the uterine body. "CD1c expression on peripheral myeloid dendritic cells was higher during menstruation in patients with endometriosis." (PMID 40508002, 2025).
fibrosis (2 papers, 2022 to 2025). the formation of excess fibrous connective tissue in an organ or tissue in a reparative or reactive process. "The Ro/e and MiloR analyses showed higher proportions of THBS1_Mono, SPP1_Macro and MKI67_Macro in the Fibrosis+ LM, whereas HSPA6_Macro, CD1C_DC and FCGR3B_Neutrophil were more prevalent in the Fibrosis− LM." (PMID 41258075, 2025). "This was an unexpected finding, as CD1c+DC-SIGN+ DCs and CD141hiCLEC9A+ DCs in the tubulointerstitium of patients with LN have previously been correlated with fibrosis and poor renal function." (PMID 35608910, 2022).
Granuloma (2 papers, 2013 to 2024). A compact, organized collection of mature mononuclear phagocytes, which may be but is not necessarily accompanied by accessory features such as necrosis. "Guinea pigs develop necrotic core granulomas, and their macrophages exhibit surface CD1b and CD1c, making them a beneficial small animal model for replicating human TB." (PMID 39949719, 2024).
Graves disease (2 papers, 2021 to 2025). Graves' disease is an autoimmune disorder that leads to overactivity of the thyroid gland (hyperthyroidism).It is caused by an abnormal immune system response that causes the thyroid gland to produce too much thyroid hormones. "CD1c+ antigen-presenting cells infiltrate lesions in Graves’ disease and Hashimoto’s thyroiditis, and T cells capable of lysing CD1c+ targets have been isolated from thyroid tissue." (PMID 40709176, 2025). "A less pronounced increase in the mDC1/pDC ratio at the third month of methimazole treatment suggests a more essential role of the shifts between CD141+ mDC2 and CD303+ pDC than CD1c+ mDC1 over the course of Graves’ disease management." (PMID 33530368, 2021).
lupus nephritis (2 papers, 2019 to 2023). Glomerulonephritis in the context of systemic lupus erythematosus. "The number of CD1C+ DCs decreased significantly in SLE patients, particularly in patients with lupus nephritis." (PMID 36755259, 2023). "Here we show that the number of peripheral tolerogenic CD1c+ dendritic cells (DCs) and the levels of serum FLT3L are significantly decreased in SLE patients especially with lupus nephritis, compared to healthy controls." (PMID 31175312, 2019). "No significant changes of absolute numbers and percentages of CD1c+DCs were observed after the treatment, indicating that the mechanism of traditional immunosuppression drugs in successfully treating lupus nephritis might not be associated with the number change of CD1c+DCs." (PMID 31175312, 2019). "Furthermore, rather than U-MSCT, the lupus nephritis patients who achieved partial remission after regular medication therapy showed no significant change of CD1c+DCs number." (PMID 31175312, 2019). "Additionally, SLE patients with lupus nephritis (LN) showed a further reduced percentage of CD1c+DCs than those without nephritis." (PMID 31175312, 2019).
metastatic prostate carcinoma (2 papers, 2016 to 2022). A carcinoma that arises from the prostate gland and has spread to other anatomic sites. "Vaccination with TAA-pulsed CD1c+ DCs for advanced stage metastatic prostate cancer was considered feasible and safe." (PMID 27853652, 2016).
neuroblastoma (2 papers, 2020 to 2022). Neuroblastoma (NB) is the most common solid, extracranial childhood tumor. "Altogether, our results suggest that CCL2 produced by neuroblastoma cells initiate the recruitment of monocytes, myeloid and plasmacytoid DCs, and that among these cells, the CD1c+ subset when activated may recruit T cells by means of CCL19/CCL22 secretion." (PMID 36923280, 2022). "Interestingly, besides MYCN amplification that is a bad prognosis factor in neuroblastoma, a recent study found that transcription of five genes including CCL19 and CD1C, could predict better prognosis." (PMID 36923280, 2022).
osteoarthritis (2 papers, 2013 to 2022). A noninflammatory degenerative joint disease occurring chiefly in older persons, characterized by degeneration of the articular cartilage, hypertrophy of bone at the margins and changes in the synovial membrane. "Elevated IP-10 and MIG levels are observed in SF of RA patients compared with control SF from patients with osteoarthritis or traumatic joint injury, and the present study shows that in vivo-activated CD1c+ mDCs from RA joints secrete high levels of IP-10 and MIG." (PMID 24286358, 2013).
sarcoidosis (2 papers, 2023 to 2025). Sarcoidosis is a multisystemic disorder of unknown cause characterized by the formation of immune granulomas in involved organs. "Some EV markers were common between HP and sarcoidosis (CD11c, CD1c, CD209, CD4, CD40, CD44, CD8)." (PMID 36835481, 2023). "Adhesion molecules for monocytes and macrophages’ marker, CD11c and CD1c, were more prominent in our sarcoidosis cohort compared to alveolar samples from HP but absent in IPF samples." (PMID 36835481, 2023).
AIDS (1 paper, 2015). A syndrome resulting from the acquired deficiency of cellular immunity caused by the human immunodeficiency virus (HIV). "With development of AIDS, numbers of CD123+ pDCs and CD16+ mDCs were significantly lower than their pre-infection levels, which was in contrast to the CD1c+ mDCs." (PMID 25915601, 2015). "Using a single 11-color flow cytometry panel, we studied changes in CD1c+ mDCs, CD16+ mDCs, and CD123+ pDCs in primary infection and until the development of AIDS." (PMID 25915601, 2015). "Although CD1c+ mDC numbers tend to be lower with AIDS compared to pre-infection, the difference was not statistically significant." (PMID 25915601, 2015). "Our results underscore the necessity of distinguishing both subsets within mDC in AIDS studies in humans, and more especially monkeys where CD11c is not a good marker for mDCs, as CD1c+ mDCs in monkeys express low-to-no CD11c." (PMID 25915601, 2015). "CD16+ mDCs and CD123+ pDCs but not CD1c+ mDCs were significantly decreased terminally with AIDS." (PMID 25915601, 2015). "Altogether our data demonstrate that SIV infection differently affects CD1c+ and CD16+ mDCs where CD16+ but not CD1c+ mDCs are depleted and might be differentially regulated in terminal AIDS." (PMID 25915601, 2015).
allergic asthma (1 paper, 2017). A asthma with a basis in a pathological type I hypersensitivity reaction. "For example, studies in patients with allergic asthma show that most of the lung CD1c+ (BDCA-1+) DCs also express CD141 (BDCA-3)." (PMID 29250057, 2017).
atherosclerosis (1 paper, 2023). A disease characterized by the build-up of fatty material and calcium deposition in the arterial wall resulting in partial or complete occlusion of the arterial lumen. "Ro 31-8220 mesylate and saracatinib induced a significant inhibition of most of the specific kinase and TF phosphorylation induced by atherosclerosis plasma, with cell specificity for monocytes and CD1c+ DCs." (PMID 37771373, 2023). "Although CCL5 was identified as a major contributor to the inflammatory response induced by plasma with atherosclerosis and, as such, it could be directly targeted, inhibition of CCL5 did not fully reverse the response in CD1c+ DCs." (PMID 37771373, 2023).
Autoimmunity (1 paper, 2023). The occurrence of an immune reaction against the organism's own cells or tissues. "For example, myeloid cytokines, such as GM-CSF, contribute to autoimmunity of the eye and GM-CSF has been shown to stimulate the differentiation of human CD1c+ subset from progenitors." (PMID 37042831, 2023). "Hence, we do not fully understand the characteristics of CD1c+ DC during autoimmunity, especially in conditions not driven by type I IFNs." (PMID 37042831, 2023).
bacterial vaginosis (1 paper, 2025). Infection caused by bacterial overgrowth in the vagina. "Here, we investigated the effect of anaerobic bacteria associated with bacterial vaginosis (BV) on HIV‐1 transmission by two distinct dendritic cell (DC) subsets, that is, inflammatory monocyte‐derived DCs (moDCs) and primary CD1c+ DCs." (PMID 40071689, 2025).
Burkitt lymphoma (1 paper, 2021). A rare form of malignant mature B-cell non-Hodgkin lymphoma. "Increased NK cell cytotoxicity in vitro against Burkitt lymphoma cells was also achieved by co-culturing human NK cells together with TLR-activated CD1c+ myeloid and plasmacytoid DCs together instead of culturing them with only one specific DC subset alone." (PMID 34054844, 2021).
celiac disease (1 paper, 2012). An autoimmune genetic disorder with an unknown pattern of inheritance that primarily affects the digestive tract. "Of antigen-presenting cells (APCs) expressing HLA-DQ molecules in the celiac disease (CD) lesion, CD11c+ dendritic cells (DCs) co-expressing the monocyte marker CD14 are increased, whereas other DC subsets (CD1c+ or CD103+) and CD163+CD11c− macrophages are all decreased." (PMID 22438948, 2012).
chronic GvHD (1 paper, 2025). "As ECP was reported to induce spontaneous release of IL-10 by myeloid CD1c+ DCs isolated from the photophoresate of refractory chronic GvHD patients, we were interested in how in vitro ECP would affect the secretion of cyto- and chemokines by sorted DCs." (PMID 40881697, 2025).
Crohn disease (1 paper, 2024). A gastrointestinal disorder characterized by chronic inflammation involving all layers of the intestinal wall, noncaseating granulomas affecting the intestinal wall and regional lymph nodes, and transmural fibrosis. "The first identification of CD1b/c “patch” implies the presence of any other motifs for known biased TCR Vβ genes, such as TRBV7-9+ T cells restricted by human CD1c or CD1d, which are associated with Crohn’s disease." (PMID 39718834, 2024).
demyelinating disease (1 paper, 2017). A broad group of disorders that affect the myelin sheaths that cover the neurons. "Higher CD1c+ B cells and lower non-classical monocyte frequencies were characteristic of more recent demyelinating disease activity (ODC and early CIS)." (PMID 28617321, 2017).
epidermal disease (1 paper, 2019). A skin disease that involves the epidermis. "The identification of molecular fingerprints of inflammatory skin states, including the enrichment of the CD1C+CD301A+ myeloid dendritic cell population in psoriatic epidermis, provides a critical step toward elucidating epidermal diseases of development, differentiation and inflammation." (PMID 31749790, 2019).
esophageal carcinoma (1 paper, 2016). A primary or metastatic malignant neoplasm involving the esophagus. "In line with the defective quantification of DCs in esophageal carcinoma, FACS results in the present study displayed that the percentages of CD1c+ mDCs, and CD141+ mDCs among PBMCs in ESCC patients were significantly lower than healthy controls." (PMID 26959879, 2016).
gastritis (1 paper, 2024). Inflammation of the stomach. "This set of data reveals that DCs are highly abundant in the gastric mucosa of H. pylori+ gastritis patients and that H. pylori infection of primary CD1c+ DCs resembles the DC activation in the context of an in vitro representation of the H. pylori infected gastric lining." (PMID 39288239, 2024).
hairy cell leukemia (1 paper, 2023). Hairy cell leukemia (HCL) is a rare type of leukemia in which abnormal B-lymphocytes are present in the bone marrow, spleen and peripheral blood. "Flow cytometry and immunohistochemistry results demonstrate CD1c antigen expression in a variety of B-cell subgroups, including mature and immature B-cell lines, as well as chronic lymphocytic leukemia (CLL) and hairy cell leukemia (HCL) (Smith, Thomas & Bodmer, 1988)." (PMID 38099311, 2023).
hereditary hemochromatosis (1 paper, 2023). An inherited metabolic disorder characterized by iron accumulation in the tissues. "For this reason, we isolated CD1c+ mDCs from fresh blood collected from patients with Hereditary Hemochromatosis (HH)." (PMID 37475964, 2023). "Due to the low yield of viable DCs from buffy coats we isolated CD1c+ mDCs from freshly drawn blood collected from patients with Hereditary Hemochromatosis (HH)." (PMID 37475964, 2023).
latent infection (1 paper, 2015). "Together these data show that only CD1c+mDC, SLAN+ DC and CD14+ monocytes were able to establish post-integration latent infection in non-proliferating CD4+ T-cells, while B-cells and CD141+ mDC were able to establish pre-integration latent infection." (PMID 26362311, 2015). "Here, we have shown that the myeloid lineage cells capable of producing latent T-cell infection include subpopulations of blood derived mDC; CD1c+, SLAN+ DC and CD14+ monocytes, and confirmed that pDC are distinct in not generating latent infection." (PMID 26362311, 2015).
leishmaniasis (1 paper, 2020). Infectious disease that is transmitted through the bite of hematophagous female phlebotomine sand flies. "Furthermore, expression of IFNA1 and IFNB1 was highest in CD1c+ DCs relative to B cells (CD19+) and monocytes (CD14+), other likely cellular sources of these cytokines in experimental leishmaniasis." (PMID 32101732, 2020).
leukoplakia (1 paper, 2024). A white patch or plaque on a mucous membrane that cannot be characterized clinically or pathologically as any other disease. "During the progression from leukoplakia to HNSCC, we found several prognostic cell subgroups, such as AURKB + epithelial cells, SFRP1 + fibroblasts, SLC7A8 + macrophages, FCER1A + CD1C + dendritic cells, and TRGC2 + NK/T cells." (PMID 38582791, 2024).
lymphoma (1 paper, 2021). A malignant (clonal) proliferation of B- lymphocytes or T- lymphocytes which involves the lymph nodes, bone marrow and/or extranodal sites. "Thus, CD1c-reactive T cells have the potential to target AML, B-ALL, T-ALL, and DLBC lymphoma expressing CD1c." (PMID 34381053, 2021).
medulloblastoma (1 paper, 2025). A malignant, invasive embryonal neoplasm arising from the cerebellum. "Other genes, like CD1C, also showed higher expression in the G4 subtype, suggesting that myeloid cell infiltration may influence medulloblastoma prognosis." (PMID 40104502, 2025).
metastatic tumor (1 paper, 2022). "We found that intratumoral DC-LAMP+ DCs as well as DC-LAMP+ and CD1c+ cells located at the tumor edge correlated positively with the size of metastatic tumor (R = 0.28, p < 0.035; R = 0.39, p < 0.002 and R = 0.27, p < 0.035, respectively)." (PMID 35955602, 2022).
mycosis fungoides (1 paper, 2020). Classical mycosis fungoides is the most common type of mycosis fungoides (MF), a form of cutaneous T-cell lymphoma, and is characterized by slow progression from patches to more infiltrated plaques and eventually to tumors. "Increased numbers of CD1a- and CD1c-expressing dendritic cells have been reported previously in MF and folliculotropic mycosis fungoides (FMF), supporting a role that lipid may be an etiology of MF." (PMID 33299887, 2020).
myelofibrosis (1 paper, 2018). A partial or complete replacement of the bone marrow stroma by fibrous tissue. "In this study, we show for the first time the co-localization of CD1c+ DCs and CD271+ MSCs in human BM from control subjects and patients with myelofibrosis, a pathology characterized by high CD271 expression." (PMID 29910810, 2018).
myeloma (1 paper, 2021). "In addition, changes of a cDC2 subtype were correlated with +1q in myeloma cells after subclustering of cDC2 (CD1c+) into three subtypes (“A”, “B”, and “C”) and cycling cDC2 cells." (PMID 34845188, 2021).
neutropenia (1 paper, 2021). A decrease in the number of neutrophils found in the blood. "In addition to the observation that G-CSF facilitates the proliferation, differentiation, and maturation of neutrophils to treat or prevent neutropenia in clinical patients, our results demonstrated that G-CSF inhibited the differentiation and proliferation of CD1c+ DCs and pDCs." (PMID 34566996, 2021).
parasitemia (1 paper, 2020). "iRBC- and TLR1/2 and TLR4 agonist-induced CD86 expression was also lower in CD1c+ cells isolated at peak parasitemia than prior to infection, while there was no change in TLR1/2 and TLR4-induced IL-12 expression and all three stimuli, iRBCs, TLR1/2 and TLR4 agonists, increased intracellular TNF." (PMID 31900030, 2020).
peritonitis (1 paper, 2017). Inflammation of the peritoneum (tissue that lines the abdominal wall and covers most of the organs in the abdomen). "These distinctive kinetics of CD14+ MØs and CD1c+ DCs during the course of PD therapy, as well as peritonitis episodes, has implied a different recruitment or differentiation processes, driven by local cytokines/chemokines under steady state and during inflammation." (PMID 28065517, 2017). "Interestingly, in patients with acute bacterial peritonitis, the increase in CD14+ MØs was much greater than CD1c+ DCs, and the ratio of MØ to DC skewed up significantly in peritonitis samples." (PMID 28065517, 2017).